IL6 (interleukin 6)
Diseases named in the same sentence as IL6 in open-access papers (continued):
Sharing a sentence is not in itself a finding about the gene and the disease.
melanoma (continued). "Among known pro-invasive mediators, we observed a positive expression and release of a conspicuous amount of IL-6 and IL-8 cytokines by melanoma CAFs, which may corroborate previously reported data showing a link between this inflammatory cytokine and melanoma invasiveness." (PMID 34298873, 2021). "Moreover, upregulation of expression of IL-12, an interleukin that has been shown to elicit significant anti-tumor activity in mice and humans, and IL-6, which acts as a growth inhibitor in early-stage melanoma, has also been observed in PBMCs co-cultured with depigmented SKMel-188." (PMID 34072104, 2021). "Thus, we sought to assess whether tumor-derived IL-1β induces the IL-6/STAT3 signaling axis in melanoma cells." (PMID 34531850, 2021). "Therefore, we tested whether replenishment of IL-6 could counteract the effects of ATF3-overexpressing HDFs on melanoma cell growth and migration." (PMID 32373541, 2020). "Similarly, IL6 blockade upregulates the expression of PD-L1 in melanoma cells." (PMID 31988638, 2020). "Furthermore, the pro-inflammatory condition and Wnt5a signaling sustained autocrine positive feedback loops that included NF-kB, IL-6, STAT3 and other immune cells, causing an immunomodulatory effect on melanoma and conferred survival and therapeutic resistance." (PMID 32244473, 2020). "Therefore, we could conclude that the inhibitory effect of ATF3-overexpressing HDFs on melanoma cell growth and migration is mainly through the IL-6/STAT3 pathway." (PMID 32373541, 2020). "Moreover, IL-6, which is also secreted by CAFs, induces IL-10 production by melanoma cells." (PMID 33171792, 2020). "However, different authors have consistently maintained that EDPs induced the production and/or secretion of IL-1α, IL-1β, and IL-6 in ligamentum flavum cells, synovial cells, and melanoma cell lines; therefore, we can assume that caspase-1 should be activated by EDPs in these cells." (PMID 31691186, 2020). "However, taken together, these data are suggestive of the important role IL-6 and IL-8 may be playing in the etiology of melanoma progression and resistance to both targeted and immunotherapies." (PMID 31781510, 2019). "Based on these results, we hypothesized that IL-6 and IL-8 produced by melanoma tumor cells participate in the expansion and recruitment of MDSCs and together would be predictive of overall survival in melanoma patients." (PMID 31781510, 2019). "Therefore, Th17 cells can promote melanoma growth via IL-6-Stat3 pathway." (PMID 30800130, 2019). "Interestingly, the IL‐6/WNT5A positive feedback loop present in parental melanoma cells is lost during the development of BRAFi resistance in melanoma cells, and therefore, IL‐6 and WNT5A signalling cascades in these cells constitute independent regulatory events." (PMID 30582770, 2019). "Additionally, other factors, such as mutated signaling pathways (MAPK or JAK/STAT), may alter the production of IL-6 and IL-8 by melanoma cells." (PMID 31781510, 2019). "To investigate whether XBP1s drives the transcription of IL-6 in melanoma cells, we analyzed the promoter sequences of human, rat and mouse IL-6 and identified a conserved putative UPR element containing the “ACGT” core sequence, a potential XBP1s binding site." (PMID 28222747, 2017). "In addition, miR-7-5p could potentially augment the anti-melanoma immune response, by blocking expression of immunosuppressive cytokines, such as IL-6." (PMID 27203220, 2016). "Along this line, recent evidences suggested that inhibition of the MAPK pathway in melanoma cells may result in the block of the production of tumor-derived immunosuppressive or proangiogenetic factors including IL-6, IL-10 and VEGF that are essential for cancer immune evasion and growth." (PMID 27563819, 2016).
melanoma (continued). "Together, our results demonstrate that WNT5A and IL-6 are connected through a positive feedback loop in melanoma cells and that the combined targeting of both molecules could serve as an effective therapeutic means to reduce melanoma metastasis." (PMID 27191257, 2016). "Indeed, catecholamine stimulation could enhance melanoma cells release of cytokines, such as IL-6, IL-8, VEGF-A and FGF-2, that sustain inflammatory, angiogenic and motility tasks." (PMID 25474135, 2015). "Our micropatterning method could clearly detect the increases of IL-6 expressions in individual B16F1 melanoma spheroids in each distance from HUVEC, while the average expression of whole B16F1 cells co-cultured with HUVEC showed no significant increase with that without HUVEC." (PMID 25058006, 2014). "Similar to the RAS/BRAF/MAPK signaling activation, down-regulation of STAT3 by lentiviral shRNA in STAT3-activated melanoma resulted in inhibition of multiple immunosuppressive cytokines, including IL-6, IL-10, and VEGF, indicating that STAT3 inhibitors may also be useful for immunotherapy." (PMID 23755373, 2013). "Hence we noticed that melanoma cells, mainly the A375 and 1205LU cell lines, which have the higher capacities of transmigration, secrete pro-inflammatory cytokines, namely GM-CSF and IL-6, which have been described to up-regulate the expression of ICAM-1." (PMID 23039186, 2012). "In line with our observations of IL6-treated cells, genetic inhibition of GLI1 expression strongly reduced IFNγ-mediated transcriptional induction of IDO1 in WM35 melanoma cells as measured by qPCR." (PMID 39962447, 2025). "Elevated IL‐6 and TNF‐α levels have been shown to increase PD‐L1 expression on melanoma cells and MDSCs, thereby reinforcing an immunosuppressive tumor milieu." (PMID 40926366, 2025). "In consideration of the production of these cytokines and their involvement in melanoma resistance to immunotherapy, we evaluated the blood levels of the cytokines TNF-α and IL-6." (PMID 40564098, 2025). "For example, elevated IL‐6 and CCL2 in BRAF‐inhibitor‐induced TIS models of melanoma correlated with increased infiltration of immunosuppressive macrophages, which dampened anti‐tumor T cell activity." (PMID 40926366, 2025). "In the current ongoing phase II study, the IL-6 inhibitor Tocilizumab in combination with Ipilimumab and Nivolumab is investigated in patients with Stage III or Stage IV Melanoma (NCT03999749)." (PMID 40523922, 2025). "A chronic inflammatory tumor microenvironment, rich in factors such as IL-6, has been reported to activate STAT3 and concomitantly stimulate the Wnt pathway in melanoma, creating a vicious cycle that promotes CSC self-sufficiency and tumor progression." (PMID 40806546, 2025). "Our findings highlighted that CCNB1 enables melanoma cells to evade NK cell-mediated immunity by activating the CDK1-STAT3 signaling axis, leading to increased IL-6 and PD-L1 expression." (PMID 40430484, 2025). "Therapeutically, targeting pathways that sustain this reprogramming, particularly the AXL/YAP, IL-6/gp130, and COX-2–PGE2 axes, represent a promising approach to reduce melanoma adaptability and improve long-term treatment outcomes." (PMID 41465101, 2025). "In human melanoma cells, inhibition of GLI1 expression prevented the induction of IDO1 expression in response to IL6/STAT3 and IFNγ/STAT1 signaling." (PMID 39962447, 2025). "PTX has been shown to suppress both constitutive and IL‐6‐induced STAT3 activation in a dose‐dependent manner, as observed in A375 melanoma cells." (PMID 40387460, 2025). "Violin plot analyses showed that IL6-JAK-STAT3, NOTCH, WNT, MAPK, EMT, E2F targets, and oxidative stress signatures were significantly upregulated in the Melanoma_High group (p < 0.001)." (PMID 40909289, 2025). "Secreted factors like IL-6 and TGF-β from CAFs reduce the expression of major histocompatibility complex (MHC) I and II molecules in melanoma cells, promoting resistance to CTL-based therapies." (PMID 40399946, 2025).
melanoma (continued). "Mechanistically, in melanoma cells, the CCNB1/CDK1 complex phosphorylates STAT3, activating the IL-6/STAT3 positive feedback loop, which upregulates PD-L1 and enables resistance to NK cell-mediated cytotoxicity." (PMID 40430484, 2025). "Our study is consistent with previous reports that higher IL-6 levels are correlated with the worse prognosis in non-small cell lung cancer (NSCLC) and melanoma patients." (PMID 40519900, 2025). "An enzyme-linked immunosorbent assay (ELISA) further demonstrated that the cGAMP-siPDL1@GalNPs significantly triggered the highest expression levels of other immune factors, including IFN-α, IL-6, IFN-γ, and TNF-α, in the B16F10 melanoma tumors and serum." (PMID 40577452, 2025). "The intricate relationship between IL-6, HCV, and melanoma highlights the need for further exploration and understanding of this cytokine’s multifaceted functions." (PMID 39336572, 2024). "Meanwhile, a correlation between IL-6 levels, phosphorylated STAT3 and CCR5 expression in tumor-infiltrating MDSC was confirmed in a RET transgenic melanoma mouse model." (PMID 38952546, 2024). "Immunomodulatory CAFs (iCAFs) displayed high expression of MMP1, MMP3, IL6, CXCL8, and IDO1, and included CAFs from melanomas, 1 SCC, and 1 BCC." (PMID 38525245, 2024). "Intriguingly, while CXCL2 was expressed by fibroblasts from all skin cancer types, melanoma-derived CAFs expressed high levels of CXCL1-3, 5, 6 and 8 and IL1B as well as IL6, whereas the expression of CXCL9-11 and 13 was high in non-melanoma CAFs." (PMID 39516494, 2024). "Serum levels of IL-6, CXCL8 and CCL2 in particular, surge during melanoma progression, while mature NKp44+ ILC3s protect against melanoma." (PMID 38410760, 2024). "For example, serum IL-1β, IL-4, IL-6, IL-10, GM-CSF, TNF-α, and sPD-L1 has significant sex-related predictive effects on OS in patients with melanoma or non-small cell lung cancer treated with ICIs." (PMID 39085893, 2024). "Serum IL-1β, IL-4, IL-6, IL-10, GM-CSF, TNF-ɑ, and sPD-L1 had a significant sex-related predictive impact on ORR, PFS and OS in melanoma and NSCLC patients treated with ICIs." (PMID 38443899, 2024). "Consistently, the clinical data revealed that melanoma with abundant E2F1, STAT3 and IL-6 preferentially induce and maintain infiltration of Th2, while simultaneously blocking Th1 cells." (PMID 39544930, 2024). "This is examined in connection with IDO-1 and IL-6 expression in response to IFN-γ or UVB stimulation, both crucial factors of the melanoma tumor microenvironment (TME)." (PMID 39062529, 2024). "We found that in response to TG or HA15 treatment, both the transcription and secretion of IL-6 and TNF-α were prominently increased in both A2058 and A375 melanoma cell lines." (PMID 38291473, 2024). "identify tumor-induced CD1c+CD14+ DC3s, increased in melanoma and NSCLC patients, originating from DC2s upon exposure to tumor-derived IL-6 and M-CSF." (PMID 38242119, 2024). "Nevertheless, E2F1-induced expression of IL6 and CD274, or elevated levels of STAT3, can mitigate the effect nurturing toward the Th2 direction in advanced stages of melanoma." (PMID 39544930, 2024). "Data-based simulations revealed that high levels of E2F1 in melanoma cells trigger autoactivation and a paracrine positive feedback loop with CD4+ T cells via secretion of IL-6 to the tumor niche to generate an inflammatory secretome." (PMID 39544930, 2024). "The polyphenols examined have shown potential as anticancer medicines targeting inflammatory cytokines since they dramatically reduce IL-6, IL-10, and TNF-α, reducing melanoma cell proliferation and migration." (PMID 38398617, 2024). "It is thought that melanoma cells reshape the TME by secreting various cytokines including TGF-β, IL-6, and IL-8 that trigger a pro-tumor N2 phenotype in neutrophils." (PMID 38533720, 2024). "MAP prediction confirmed the effect of selected markers, especially IL6 and CTLA4, on the activation of melanoma disease." (PMID 39336572, 2024).
melanoma (continued). "An in silico analysis identified key molecular players, including IL-6 and CTLA4, in the HCV-melanoma network." (PMID 39336572, 2024). "The present study evaluated the prognostic significance of serum GDF-15 and IL-6 levels in patients undergoing immunotherapy for advanced malignancies, including NSCLC, RCC, and malignant melanoma." (PMID 39766045, 2024). "In melanoma, IREIα-XBP1 signalling is observed to promote M2 macrophage polarization, including the upregulation of interleukin 6 (IL-6), IL-23, and arginase 1 expression, leading to tumour immunosuppression." (PMID 38297380, 2024). "In melanoma patients, high serum concentrations of C-reactive protein (CRP) and the proinflammatory cytokine IL-6 before start of PD-1 blockade therapy correlate with poor treatment outcome." (PMID 38967829, 2024). "The goal was to explore the effect of interleukin-6 (IL6) and C reactive protein (CRP) on malignant melanoma (MM) using two-sample Mendelian randomization." (PMID 38952546, 2024). "Novel serum biomarkers, including LDH, CRP, sPD-L1, and IL-6, and metabolite signatures like NGS hold promise in predicting responses to ICIs in melanoma." (PMID 39282490, 2024). "Six STAT3-inducing cytokines (IL-6, IL-11, MIF, PDGF-AA, OPN, and MCP-1), all expressed by melanoma, were tested for their ability to induce these alterations in microglia cells." (PMID 37296634, 2023). "Mechanistically, BET inhibitors sensitize melanoma cells to sunitinib by inhibiting the BRD4/GDF15 axis and the BRD4/IL6/STAT3/GDF15 axis." (PMID 36720918, 2023). "The interrelationship between high IL6 and IL8 production and melanoma progression has been well documented." (PMID 37762344, 2023). "In general, CAFs aid melanoma progression and metastasis by secreting inflammatory cytokines (e.g., CCL2, IL-6, and IL-8) and pro-angiogenic factors (e.g., VEGF), and by promoting an invasive melanoma cell phenotype." (PMID 37345186, 2023). "In experiments targeting melanoma, simultaneous inhibition of IL-6 and IL-8 is sufficient to fully inhibit CAF-induced human melanoma cell invasiveness." (PMID 37046676, 2023). "Nevertheless, melanoma expresses high NLRP3-derived IL-1β expression, which specifically induces pSTAT3 and amplifies IL-6 secretion through the IL-1β/IL-6/STAT3 axis in vivo, leading to a further expansion of MDSCs." (PMID 36911674, 2023). "We employed 2D co-cultures of mCherry-labeled melanoma cells (from our four cell lines) with GFP-labelled microglia cells and asked if IL-6 affects cell proliferation of either cellular partner or of both." (PMID 37296634, 2023). "We next measured the effect of the IL-6/JAK/STAT3 inhibitors αIL-6R, Baricitinib, and Stattic on the proliferation of melanoma and microglia cells in 2D and 3D co-cultures." (PMID 37296634, 2023). "It is known that melanoma cells in the TME are the main producers of IL-8, while fibroblasts in monocultures predominantly secrete IL-6 and, when CAFs were co-cultured, IL-6 and IL-8 secretion was detectable in the media." (PMID 37627054, 2023). "IL-6/STAT3 pathway inhibitors diminished the pro-metastatic functions of microglia and reduced melanoma progression." (PMID 37296634, 2023). "In the B16.F10 mouse melanoma model, the TLR2 agonist Pam3CSK4 induced MCs to release cytokines such as IL-6 and CCL3, which mediated a direct antiproliferative effect on tumor cells and the recruitment of NK and T cells, respectively." (PMID 37376140, 2023). "Marked downregulation of expression of TREM1 and known TREM1 target genes (NFKB1, CCL20, IL6, and CXCL8) was determined in melanoma PDX models treated with VJDT." (PMID 37651197, 2023). "We next tested the effect of IL-6/JAK/STAT3 pathway inhibition on the ability of YDFR.CB3 and DP.CB2 melanoma cells to form spheroids with microglia cells." (PMID 37296634, 2023). "Mechanistically, BET inhibitors sensitize melanoma cells to sunitinib by inhibiting the BRD4/GDF15 axis and BRD4/IL6/STAT3/GDF15 axis." (PMID 36720918, 2023).
melanoma (continued). "In contrast, inhibiting STAT3 by specific inhibitors or STAT3 siRNA decreases the levels of IL-6, IL-10, and VEGF mRNA expression in melanoma cells." (PMID 36979654, 2023). "In melanoma cells, TNFα/TNFR1 signaling mediates the significant upregulation of the pro-inflammatory cytokine IL6 gene supported by the TNF-α overexpression." (PMID 36829966, 2023). "Adipocyte-created IL-6 and TNF-αmiR-211 promote the miR-211-repressed translation of TβR I mRNA to enhance the cellular responsiveness and metastasis of melanoma." (PMID 35461253, 2022). "The mRNA expression level of inflammatory cytokines such as IL-1β, IL-6, and TNF-α confirmed the macrophage activation state upon the treatment with the acid EV derived from all the three melanoma cell lines used." (PMID 36291876, 2022). "For example, the combination of anti-PD-L1 and anti-IL-6 antibodies increases IFN-γ and Th1 in melanoma mice, turning off IL-6/STAT3 pathway, which further activates IFN-γ/STAT1 for causing local inflammation." (PMID 36120342, 2022). "A previous phase II trial with nivolumab in melanoma cases has shown that IFN‐γ, IL‐6, and IL‐10 levels in the responders were significantly increased when compared to non-responders (p < 0.0001, p = 0.0007, and p < 0.0001, respectively)." (PMID 35992783, 2022). "One study reported that B cells from melanoma patients' peripheral blood express TNF-α and/or IL-6, and TNF-α transcripts from single B cells extracted from melanoma metastases were associated with reduced responsiveness to checkpoint inhibitor immunotherapy." (PMID 35909944, 2022). "Our results showed that both CD4 and CD8 T cell subsets were equally capable of inhibiting melanoma-conditioned macrophage-derived CCL2, VEGF, and IL-6 in a contact-independent manner." (PMID 35265066, 2022). "Bevacizumab, an antiangiogenic therapy, has been observed in melanoma to increase circulating CD8+ T cells and interleukin-6 levels so as to change the TME in combination with chemotherapy." (PMID 35582532, 2022). "Data from CheckMate 064, 066 and 067 also found that elevated levels of IL-6 and CRP played both an indirect and a direct suppressive role, accounting for the poor outcomes of melanoma patients receiving single agent and combination checkpoint inhibition." (PMID 35185894, 2022). "Other studies on SNPs in melanoma genes demonstrated that various cytokines (TNF-a, IL-6, IL-10, IFN-c, and TGF-b1) are involved in melanoma progression and immune escape." (PMID 35334544, 2022). "Interfering Twist1 inhibited epithelial-mesenchymal transition (EMT) and limited lipopolysaccharide-induced inflammation, migration, and invasion in A2058 melanoma cells with the decrease of MMP1/9, VEGF, TNF-α, and IL-6." (PMID 35321317, 2022). "Particularly, serum levels of IL-6, CXCL8 and CCL2 have been previously shown to increase during melanoma progression." (PMID 35173725, 2022). "IL-6, CXCL8 and VEGF have been widely demonstrated to be related to worse clinical outcome in melanoma." (PMID 35173725, 2022). "Together, these studies show that elevated S100B suppresses IL6 and STAT3 transcriptional activity in malignant melanoma." (PMID 34411141, 2021). "Studies using a melanoma brain metastasis immunocompetent mouse model revealed an upregulation in proinflammatory cytokines CXCL10, CCL17, CCL2, IL6, and IL-1β." (PMID 33466236, 2021). "Measurements included LDH, interleukin (IL)-6, IL-1β, IL-17, C-reactive protein (CRP) and tumor necrosis factor (TNF)-alpha as well as tumor markers S100 and melanoma inhibitory activity (MIA)." (PMID 33837821, 2021). "In previous studies on melanoma, NE upregulates the expression of the protumorigenic cytokines VEGF, IL-8, and IL-6 and metalloproteases in tumor cell lines." (PMID 33855088, 2021).